RNU2-35P (RNA, U2 small nuclear 35, pseudogene)
Gene: Small nuclear RNA gene on chromosome 11 (125,649,746 to 125,649,887, forward strand). Ensembl gene ENSG00000252255.
Homologues: Orthologues: chimpanzee U2 (100% identical), macaque U2 (58% identical), pig U2 (49% identical), pig U2 (44% identical), rat LOC120099528 (42% identical), guinea pig U2 (40% identical). Paralogues in human: RNU2-26P (57% identical), RNU2-57P (57% identical), RNU2-2 (56% identical), U2 (56% identical), RNU2-14P (56% identical), RNU2-28P (56% identical), RNU2-32P (55% identical), RNU2-4P (55% identical), RNU2-52P (55% identical), RNU2-64P (55% identical), RNU2-48P (54% identical), RNU2-56P (54% identical), and 65 more.